GPX6 (glutathione peroxidase 6)
Synonyms: GPx-6; GSHPx-6; GPX5p; GPXP3; dJ1186N24; dJ1186N24.1
Tractability: Antibody: UniProt places it where antibodies can reach, with medium confidence; UniProt predicts a signal peptide or a membrane-spanning region; its Gene Ontology location is reachable by antibodies, with medium confidence.
Gene: Protein-coding gene on chromosome 6 (28,503,296 to 28,528,215, reverse strand). Ensembl gene ENSG00000198704.
Subcellular location: Secreted
Pathways (Reactome):
Cellular responses to stimuli: Detoxification of Reactive Oxygen Species
Gene Ontology:
Molecular function: glutathione peroxidase activity; peroxidase activity
Biological process: cellular response to oxidative stress; cellular oxidant detoxification; response to oxidative stress
Cellular component: extracellular region
Genetic constraint (gnomAD): Loss-of-function variants: 17 observed, 18.93 expected, observed/expected ratio (o/e) 0.9, 90% interval 0.61 to 1.35. The synonymous counts are far from expectation, so gnomAD's model fits this gene poorly and the ratio says little. Missense variants: 220 observed, 247.54 expected, observed/expected ratio (o/e) 0.89, 90% interval 0.8 to 0.99. Synonymous variants: 71 observed, 96.8 expected, observed/expected ratio (o/e) 0.73, 90% interval 0.61 to 0.89.
Homologues: Orthologues: chimpanzee GPX6 (97% identical), macaque GPX6 (94% identical), pig GPX6 (82% identical), dog GPX6 (81% identical), rabbit GPX6 (76% identical), mouse Gpx6 (72% identical), rat Gpx6 (67% identical), Caenorhabditis elegans gpx-3 (33% identical), Caenorhabditis elegans gpx-5 (33% identical), Caenorhabditis elegans gpx-2 (25% identical), zebrafish gpx4a (24% identical), Caenorhabditis elegans gpx-4 (18% identical), and 1 more. Paralogues in human: GPX3 (70% identical), GPX5 (67% identical), GPX1 (36% identical), GPX2 (34% identical), GPX4 (24% identical), GPX7 (24% identical), GPX8 (24% identical).
Diseases named in the same sentence as GPX6 in open-access papers:
GPX6 is named in the same sentence as 18 diseases in open-access papers, as found by Europe PMC text mining. Sharing a sentence is not in itself a finding about the gene and the disease. The quoted sentences say what the papers report.
breast carcinoma (3 papers, 2014 to 2020). "As studies of the functions of GPx5, GPx6 and GPx7 in the development of breast cancer are limited, it is difficult to determine their underlying mechanisms." (PMID 32571353, 2020). "We have found six polymorphisms in OGG1, GPX6, SOD3, TXN and XDH genes significantly associated with predisposition to breast cancer." (PMID 25416100, 2014). "The gene-gene interactions demonstrated a significant four-variant interaction among rs406113 (GPX6), rs974334 (GPX6), rs105213 (OGG1) and rs2284659 (SOD3) (p-value = 0.0008) with high-risk genotype combination showing increased risk for breast cancer (OR = 1.75 [95% CI; 1.26-2.44])." (PMID 25416100, 2014). "A four-way interaction found that between rs406113 on the GPX6 gene, rs974334 on the GPX6 gene, rs1052133 on the OGG1 gene and rs2284659 on the SOD3 gene predicts breast cancer with a testing balance accuracy of 0.5267." (PMID 25416100, 2014). "However, the other four GPXs family genes (GPX1, GPX5, GPX6 and GPX7) showed no statistical diagnostic values in breast cancer." (PMID 32782436, 2020). "GPX4, GPX6 and GPX7 had no significant predictive values for prognosis of breast cancer." (PMID 32782436, 2020).
Huntington disease (2 papers, 2018 to 2023). Huntington disease (HD) is a rare neurodegenerative disorder of the central nervous system characterized by unwanted choreatic movements, behavioral and psychiatric disturbances and dementia. "Moreover, in a mouse model, molecular and behavioral phenotypes linked with Huntington’s disease were drastically reduced after overexpression of GPX6." (PMID 29758013, 2018). "However, applying SLIC (Sequence-and Ligation—Independent Cloning, a method for sequence-and ligation-independent cloning) in a study on Huntington’s disease, it has been identified that toxicity of huntingtin mutation is modulated via age-regulated GPX6 gene." (PMID 29758013, 2018). "Moreover, it has been described that detoxification enzymes such as GPx-6 significantly increased in the early stage of neurodegenerative diseases such as Parkinson’s and Huntington’s diseases as a compensatory mechanism for the increment of various toxic factors after the onset of the disease." (PMID 37761814, 2023).
Arthritis (1 paper, 2020). Inflammation of a joint. "We examined specific glutathione pathway genes including GSTM6, GSTM3, and GPX6, which were differentially expressed in PON1Tg mice compared to WT mice after arthritis induction in our initial pathway analysis." (PMID 33033318, 2020).
hearing loss (1 paper, 2014). "These three genes were: Hspb1 (p = *0.0345, F = 3.79, df = 2,29) and Gpx6 (p = **0.0011, F = 8.644, df = 2,29) that showed significant up-regulation and Txnrd1 (p = 0.6575, F = 0.4254, df = 2,29) that showed down-regulation with age and hearing loss." (PMID 24587312, 2014).
Infertility (1 paper, 2018). "The biological processes significantly represented among differentially expressed genes included mitochondrial function (Mrps31 and Trit1), cell senescence (Gpx6, Lamtor1 and Hist1h1e), cell growth (Hormad1 and Hormad2), infertility (Sycp3), and embryo development (Gli3)." (PMID 29851234, 2018).
ischemia (1 paper, 2023). A hypoperfusion of the BLOOD through an organ or tissue caused by a PATHOLOGIC CONSTRICTION or obstruction of its BLOOD VESSELS, or an absence of BLOOD CIRCULATION. "Furthermore, Il9, Gpx5, and Gpx6 were completely disconnected from the main gene cluster in the ischemia+Placebo network." (PMID 37426668, 2023).
Obesity (1 paper, 2020). Accumulation of substantial excess body fat. "We found two haplotypes associated with obesity by BMI (in GPX3 and in GPX5 and GPX6) and five haplotypes associated with obesity by PBF (in GPX3, in PON1, and in PON2 and PON3)." (PMID 32752212, 2020). "Six haplotypes were significantly associated with obesity; two of them (one in GPX3 and the other one in GPX5 and GPX6) showed this association in a protective direction when obesity was classified by BMI." (PMID 32752212, 2020). "We found six haplotypes associated with obesity—two of them (one in GPX3 and the other in GPX5 and GPX6) in a protective direction when obesity was classified by BMI." (PMID 32752212, 2020). "In this study we found six haplotypes associated with obesity, two of them (one in GPX3 and the other in GPX5 and GPX6) when obesity was classified by BMI." (PMID 32752212, 2020).
steatosis (1 paper, 2023). Increased lipid within the cytoplasm of cells. "In HepG2 cells with steatosis, PGAM5 knockdown reduced insulin sensitivity, increased mTOR phosphorylation and reduced the expression of NRF2, catalase (CAT), HO-1 and GPX6." (PMID 37605246, 2023).
tumor (2 papers, 2023). "All selenoproteins except for GPX6 were expressed in tumour tissues." (PMID 37741974, 2023).
infection (1 paper, 2025). The state of being infected such as from the introduction of a foreign agent such as serum, vaccine, antigenic substance or organism. "In our study, the greater abundance of GPX6 in the SLB-susceptible genotype suggests that the plants may have experienced elevated levels of ROS due to pathogen infection, triggering the synthesis of GPX6 as a reactive antioxidant defense." (PMID 39942988, 2025).
GPX6 also shares sentences with these, for which no sentence is quoted: cancer (3 papers); cervical carcinoma (1); Epithelial Ovarian Cancer (1); neurodegenerative disease (1); neurological disease (1); Parkinson’s (1); presbycusis (1); rectal cancer (1).